EFHD1 (EF-hand domain family member D1)
Description:
Acts as a calcium sensor for mitochondrial flash (mitoflash) activation, an event characterized by stochastic bursts of superoxide production. May play a role in neuronal differentiation (By similarity).
Synonyms: SWS2; PP3051; FLJ13612; MST133; MSTP133
Tractability: PROTAC: ubiquitination databases record sites on it; its protein half-life has been measured.
Gene: Protein-coding gene on chromosome 2 (232,606,057 to 232,682,781, forward strand). Ensembl gene ENSG00000115468.
Subcellular location: Mitochondrion inner membrane
Subcellular location (Human Protein Atlas): Golgi apparatus; Nucleoli fibrillar center
Gene Ontology:
Molecular function: calcium ion sensor activity; protein binding; calcium ion binding
Biological process: regulation of cellular hyperosmotic salinity response
Cellular component: Golgi apparatus; mitochondrial inner membrane; mitochondrion
Genetic constraint (gnomAD): Loss-of-function variants: 10 observed, 15.14 expected, observed/expected ratio (o/e) 0.66, 90% interval 0.41 to 1.12. The synonymous counts are far from expectation, so gnomAD's model fits this gene poorly and the ratio says little. Missense variants: 310 observed, 283.08 expected, observed/expected ratio (o/e) 1.1, 90% interval 1 to 1.2. Synonymous variants: 153 observed, 121.3 expected, observed/expected ratio (o/e) 1.26, 90% interval 1.11 to 1.44.
Homologues: Orthologues: chimpanzee EFHD1 (100% identical), macaque EFHD1 (96% identical), pig EFHD1 (85% identical), mouse Efhd1 (82% identical), dog EFHD1 (81% identical), rat Efhd1 (79% identical), rabbit EFHD1 (75% identical), guinea pig EFHD1 (74% identical), tropical clawed frog efhd1 (67% identical), zebrafish efhd1 (62% identical), Drosophila melanogaster Swip-1 (50% identical), Caenorhabditis elegans efhd-1 (46% identical), and 1 more. Paralogues in human: EFHD2 (67% identical).
Diseases named in the same sentence as EFHD1 in open-access papers:
EFHD1 is named in the same sentence as 21 diseases in open-access papers, as found by Europe PMC text mining. Sharing a sentence is not in itself a finding about the gene and the disease. The quoted sentences say what the papers report.
colorectal cancer (5 papers, 2014 to 2025). A primary or metastatic malignant neoplasm that affects the colon or rectum. "Indeed, expression profiling of a subset of tumor types, such as clear cell renal cell carcinoma (ccRCC) and colorectal cancer, has recently proposed the expression level of EFHD1 as a prognostic factor and biomarker." (PMID 39261663, 2024). "Aberrant promoter methylation of EFHD1 was highly positive in colorectal cancer plasma samples, and they might be useful in detection of early-stage colorectal cancer." (PMID 36072430, 2022). "Takane et al25 found the aberrant promoter methylation of PPP1R3C and EFHD1 in plasma of colorectal cancer (CRC) patients, and verified that both of them could be potential detection markers for CRC." (PMID 30039914, 2018).
breast carcinoma (3 papers, 2018 to 2024). "EF-hand Domain Family Member D1 (EFHD1) is shown to be overexpressed in breast cancer and is reported to serve as a potent breast cancer-specific RNA signature." (PMID 33761889, 2021).
Clear Cell Renal Cell Carcinoma (3 papers, 2021 to 2025). "EFHD1 was recently shown to bind MCU in clear cell renal cell carcinoma (ccRCC), and it therefore provides a great example of the predictive power of our resource." (PMID 39261663, 2024). "Additionally, the aberrant expression of EFHD1 has been observed in clear-cell renal cell carcinoma." (PMID 39895792, 2025).
osteosarcoma (2 papers, 2024 to 2025). A usually aggressive malignant bone-forming mesenchymal neoplasm, predominantly affecting adolescents and young adults. "Similarly, studies have demonstrated that EFHD1 inhibits mPTP opening and enhances mitochondrial function through SLC25A6, reducing mitochondrial Cyt c release and promoting the proliferation and chemoresistance in osteosarcoma." (PMID 40841355, 2025).
renal cell carcinoma (2 papers, 2011 to 2023). "Similarly, the reduction of MCU expression in renal cell carcinoma, through the overexpression of the EF-hand domain family member D1 protein (EFHD1), and a negative regulator of MCU activity, leads to the reduction in cell migration and metastatic potential." (PMID 37759703, 2023). "Interestingly, EFhd1 expression is repressed in renal cell carcinoma (RCC)." (PMID 21244694, 2011).
craniosynostosis (1 paper, 2023). Craniosynostosis is defined as the premature fusion of one or more cranial sutures leading to secondary distortion of skull shape resulting in skull deformities with a variable presentation. "There was a single gene, EFHD1, that was significantly decreased across all four phenotypes of craniosynostosis compared to controls." (PMID 36982425, 2023).
melanoma (1 paper, 2011). A malignant, usually aggressive tumor composed of atypical, neoplastic melanocytes. "In contrast, EFhd1 is present in tumour tissues from patients with stage III and IV melanoma and increased expression of EFhd1 is significantly associated with shorter patient survival times." (PMID 21244694, 2011).
mental disorder (1 paper, 2017). A disease that has its basis in the disruption of mental process. "We also observed hypomethylation of EFHD1 to be associated with mental disorder." (PMID 28850114, 2017).
pancreatic carcinoma (1 paper, 2011). "Conversely, reduction of SOD2 abundance causes increased EFhd1 expression in a human pancreatic carcinoma cell line (MIA-PaCa2)." (PMID 21244694, 2011). "Interestingly, ectopic expression of manganese superoxide dismutase 2 (SOD2), a mitochondrial enzyme that inactivates superoxide to protect cells from oxidative damage, induces down-regulation of EFhd1 in a pancreatic carcinoma cell line." (PMID 21244694, 2011).
prostate tumors (1 paper, 2016). "Of these, EFHD1, MLPH, NAALADL2 and KLK15 are significantly upregulated while others are downregulated in prostate tumors compared to normal samples." (PMID 27409348, 2016).
Right ventricular cardiomyopathy (1 paper, 2025). Right ventricular dysfunction (global or regional) with functional and morphological right ventricular abnormalities, with or without left ventricular disease. "EFHD1 high expression was enriched in the arrhythmogenic right ventricular cardiomyopathy pathway, while low expression was enriched in the allograft rejection pathway." (PMID 40441253, 2025).
schizophrenia (1 paper, 2017). A major psychotic disorder characterized by abnormalities in the perception or expression of reality. "Elevated expression of CNTN2 and EFHD1 was specifically found in disorganized schizophrenia." (PMID 28809853, 2017).
tumor (14 papers, 2011 to 2025). "EFHD1 inhibits cell migration and invasion in vitro and tumor metastasis in vivo by modulating the Hippo signaling pathway." (PMID 39895792, 2025). "The results showed that EFHD1 expression in paracancerous tissue samples was noticeably higher than that in tumor tissue samples." (PMID 39895792, 2025). "EFHD1 overexpression significantly slowed the progression of lung metastasis, whereas EFHD1 knockdown accelerated tumor metastasis." (PMID 39895792, 2025). "H&E staining of tumor sections revealed intact cellular structures and nuclei in both the control and EFHD1-silencing groups, while the EFHD1-overexpressing group exhibited pronounced tumor necrosis." (PMID 39895792, 2025). "Analysis of the GEPIA datasets showed that EFHD1 was less expressed in CRC tumor tissues than in normal tissues." (PMID 39895792, 2025). "EFHD1 markedly suppressed cell proliferation, migration, and invasion in vitro and inhibited tumor growth and metastasis in vivo." (PMID 39895792, 2025). "EFHD1, a mitochondrial calcium-binding protein, regulates calcium homeostasis and suppresses tumor metastasis via the Hippo/YAP pathway." (PMID 40018519, 2025). "For example, previous genomic studies have validated that EFHD1 is highly expressed in breast cancer 7, making it a promising target for tumor prediction." (PMID 39895792, 2025). "Our models demonstrated that EFHD1 and SLC25A18 were significantly associated with the cell cycle (R2 = 0.790), while SASH1 and FAM110B showed a notable association with tumor stemness (R2 = 0.522)." (PMID 40018519, 2025). "In this study, EFHD1 expression in paracancerous tissue samples was noticeably higher than that in tumor tissue samples." (PMID 39895792, 2025). "H&E staining of lung tissues showed that the number of lung tumor nodules in the EFHD1-overexpressing group was markedly lower than that in the control group, whereas there were more tumor nodules in the EFHD1-silencing group." (PMID 39895792, 2025). "Knockdown of EFHD1 in 143BR cells reduced tumor volume and tumor weight compared with 143BR-shV cells." (PMID 38795203, 2024). "Similar with results from TCGA-KIRC and GSE126964, the expression of ALDOB, ESRRG, and EFHD1 were much lower in tumor cells than that in other intrinsic renal cells." (PMID 34660292, 2021). "Methylation status of PPP1R3C and EFHD1 was compared with other clinicopathological factors including sex, age, tumor stage, and tumor locations." (PMID 24861485, 2014). "In addition, SIK3 expression was lower in CRC tumor tissues than in normal tissues, and EFHD1 overexpression significantly increased the protein level of SIK3." (PMID 39895792, 2025). "Despite its promising potential, EFHD1 has yet to be explored for clinical anti-tumor applications." (PMID 39895792, 2025). "Recently, the role of EFHD1 in tumor progression was revealed." (PMID 39895792, 2025). "Whereas EFhd1 has been proposed to exhibit tumour suppressing functions in RCC, growth promoting functions may be associated with other tumours." (PMID 21244694, 2011). "Whether EFhd1 is actually a survival promoting or tumour suppressing factor may depend on the cell type and environmental context." (PMID 21244694, 2011). "Additionally, EFHD1 limited CRC tumor growth and lung metastasis in vivo." (PMID 39895792, 2025). "However, there are few data showing that EFHD1 plays a role in tumor progression." (PMID 38795203, 2024). "Therefore, it is reasonable to generate and cross EFhd2 knockout and transgenic mice with the respective Efhd1 mice and analyze the impact in function and development, especially with regard to the immune and nervous system, as well as the progression of tumours." (PMID 21244694, 2011). "Notably, EFHD1 and SLC25A18 exhibited strong positive correlations with cellular processes related to the cell cycle (Cor = 0.368/0.385, P < =0.001), whereas SASH1 and FAM110B were found to be closely associated with tumor stemness (Cor =0.328/0.427, P < =0.001)." (PMID 40018519, 2025).
tumor (continued). "HIGD1A, EFHD1, and PPARGC1A were found to be overexpressed in normal tissue, whereas TRAP1 and P4HA1 were found to be overexpressed in CRC tumor tissue (p < .001)." (PMID 37903487, 2024). "Regardless of luminal subtype (A/B), LM cells had increased expression of ELOVL5, EFHD1, NEK10, LYPD6 and NOVA1, among others, relative to the tumor cells." (PMID 39478117, 2024). "TRAP1 and P4HA1 are highly expressed at the intracellular level, whereas PPARGC1A, EFHD1, and HIGD1A are only expressed by a minority of tumor cells." (PMID 37903487, 2024). "In tumor suppressor genes such as O6-methyguanine-DNA methyl transferase (MGMT), bone morphogenetic protein 3 (BMP3), and EFHD1 (EF-hand domain family member D1), methylation at certain CpG sites results in gene suppression and the formation of malignancy." (PMID 38380073, 2024). "The expression of three other genes was reduced 2-fold to 6-fold in tumor versus adjacent liver (p < 0.05, t test, df = 4), including a 3′ UTR insertion in SLC2A1 and intronic insertions in PHGDH and EFHD1." (PMID 23540693, 2013). "Additionally, EFHD1 overexpression reduced nuclear YAP1, nuclear TAZ, and TEAD1 levels, thereby preventing YAP1/TAZ nuclear translocation and interaction with TEAD1, a key process in tumor progression." (PMID 39895792, 2025). "Spermatogenesis associated 18 (SPATA18) and EF-hand domain family member D1 (EFHD1), as opposed to SPOCK1, GTSE1 and ADAM12, are two tumor suppressors both involved in mitochondria functions." (PMID 37370817, 2023). "In good agreement with these previous observation, methylation of PPP1R3C and EFHD1 in plasma DNA samples were detected commonly in CRC patients, regardless of sex, age, or tumor location." (PMID 24861485, 2014).
cancer (6 papers, 2013 to 2025). A tumor composed of atypical neoplastic, often pleomorphic cells that invade other tissues. "Importantly, the heterogeneous expression pattern of EFHD1 among human tissues and cancer cell lines could also explain why EFHD1 loss- or gain-of-function would affect [Ca2+]mt homeostasis to different extents in different cell types." (PMID 39261663, 2024). "EFHD1, an EF-hand superfamily protein, has recently received considerable attention in cancer research 7-9, although its anti-cancer effect in CRC remains poorly understood." (PMID 39895792, 2025). "The expression of TRAP1 in pan‐cancer was shown to be substantially inversely linked with that of HIGD1A and EFHD1, and positively correlated with that of PPARGC1A, according to a correlation study of 5 MRGs." (PMID 37903487, 2024). "As a selective determinant of cell survival and cancer progression, EFHD1 surely represents an important therapeutic target for further investigations." (PMID 39261663, 2024). "Based on these findings, we speculated that EFHD1 may exert anti-cancer effects in CRC by regulating SIK3 expression." (PMID 39895792, 2025). "Since the sustained increase of [Ca2+]mt has been shown to promote cell death, we speculated that high EFHD1 expression would protect cancer cells from pro-apoptotic triggers." (PMID 39261663, 2024). "We next set out to evaluate the relevance of EFHD1 more broadly in cancer biology." (PMID 39261663, 2024). "However, few studies have investigated the anti-cancer effects of EFHD1 in CRC." (PMID 39895792, 2025). "EF-hand domain-containing protein D1 (EFHD1) and salt-inducible kinase 3 (SIK3) have been studied in several cancer types." (PMID 39895792, 2025).
mitochondrial disease (1 paper, 2025). "The identification of mitochondrial disease-specific markers (EFHD1, SASH1, FAM110B, and SLC25A18) highlights shared mechanisms, such as oxidative phosphorylation, calcium signaling, and immune responses, that can serve as therapeutic targets in both AD and GBM." (PMID 40018519, 2025).
EFHD1 also shares sentences with these, for which no sentence is quoted: B cell lymphomas (1 paper); breast tumor (1); cervical cancer (1); heart failure (1); infection (1); Primary immunodeficiency (1).